IRF3 (interferon regulatory factor 3)
Diseases named in the same sentence as IRF3 in open-access papers (continued):
Sharing a sentence is not in itself a finding about the gene and the disease.
viral infection (continued). "In contrast to IRF7, knockdown of IRF3 did not affect the viral production even though IRF3 and IRF7 are considered to play essential roles in innate immune responses to virus infections." (PMID 23555825, 2013). "Overall, these results strongly support a specific effector role of virus-induced secretion of WNT2B and WNT9B ligands in innate immunity, acting in a feedback inhibition of IRF3- and NF-κB-dependent IFNB1 response to virus infection." (PMID 23785285, 2013). "DNA-PKcs was able to phosphorylate interferon regulatory factor 3, which is critical for type I IFN expression in response to viral infection." (PMID 23533581, 2013). "Consistent with our previous report that OASL1 specifically inhibits the translation of IRF7 mRNA upon viral infection, IRF7 protein levels were much higher in Oasl1 KO cells during the days, whereas IRF3 protein levels were similar between WT and KO spleens." (PMID 23874199, 2013). "We also determined the dynamics of IRF3 and IRF7 recruitment to the IFN-A gene promoters in the course of virus infection." (PMID 22685561, 2012). "Following viral infection K69R and K154R reconstituted cells displayed reduced enzyme activity as monitored by either TBK1 or IRF3 phosphorylation." (PMID 23028469, 2012). "Taken together, these data show that poly I∶C–induced stochastic IFNβ expression depends on the abundance of both poly I∶C and signaling pathway protein MDA5 as well as IRF3/IRF7, which is similar to what was found in the case of virus infection." (PMID 22291574, 2012). "Both IRF3 and IRF7 play distinct and essential roles in the IFNα/β response to eliminate the viral infection." (PMID 22206025, 2011). "Activation of IFNβ gene expression requires IRF3, IRF7 and NFκB, but we find that the levels of IRF7 and p65 remain relatively constant during the course of viral infection." (PMID 21677781, 2011). "Virus infection induces phosphorylation of IRF-3 on specific C-terminal serine residues and permits cytoplasmic-to-nuclear translocation of IRF-3." (PMID 19592477, 2011). "Another common pathway upstream of IRF3 activation is the engagement of TLR3 by viral dsRNA, which is produced as a replication intermediate during viral infection." (PMID 21436888, 2011). "Taken together, these findings support the idea that NF-κB and c-Jun sustain basal/early ifnβ expression, while IRF-3 and IRF-7 instead dominate IFN-β production following virus infection." (PMID 22022260, 2011). "Two reports showed that Vpr downregulates the expression of Interferon regulatory factor 3 (IRF-3), a factor which is essential for interferon (IFN) beta production in response to viral infection." (PMID 20380700, 2010). "As IRF-3 and IRF-7 are key regulators of the type I IFN response to viral infection, we also compared the DKO phenotype with congenic IFN-αβR−/− mice." (PMID 19798431, 2009). "The idea that VP35 makes use of the cellular SUMO system is further supported by our recent report that both IRF3 and IRF7 are SUMOylated following viral infection." (PMID 19557165, 2009). "In view of the fact that VP35 inhibits IRF3's ability to stimulate IFN transcription and that IRF3 is SUMOylated after viral infection, it was of interest to test if VP35 increases SUMOylation of IRF3 as well." (PMID 19557165, 2009). "Supporting the view that SUMOylation is involved in the IFN transcription, we recently reported that IRF3 and IRF7 are modified by SUMO1 through SUMO3 in fibroblasts after viral infection." (PMID 19557165, 2009). "Interferon regulatory factors (IRF)-3 and IRF-7 are master transcriptional factors that regulate type I IFN gene (IFN-α/β) induction and innate immune defenses after virus infection." (PMID 19798431, 2009). "Host recognition of viral infection normally activates multiple evolutionarily conserved signaling pathways, such as NF-κB and the IFN-regulatory factors 3 and 7 (IRF3 and IRF7)." (PMID 18617992, 2008).
viral infection (continued). "In many viral infections, IFN-independent ISG induction is mediated by the IRF-3 phosphorylation, homodimerization, and nuclear translocation." (PMID 18604270, 2008). "As expected, IRF3 KO cells failed to produce either IFNλ1 or IFNλ2/3 under basal conditions or upon viral infection." (PMID 41525418, 2026). "Our results suggest that during viral infection, activation of IRF3 does not automatically result in IFN responses at the level of individual cells, but that other factors, such as NF-κB and AP-1, are limiting for type I IFN induction." (PMID 41671320, 2026). "CSFV infection triggers the secretion of cytokines and the synthesis of antibodies; this viral infection activates downstream signaling molecules, including MAVS, IRF3, and NF-κB, through the engagement of receptors such as RIG-I, MDA5, and TLR3 (with a primary focus on RIG-I)." (PMID 40001503, 2025). "What calls for special attention is that bat TBK1 constitutively enhances the IRF3-mediated interferon pathway under basal conditions (in the absence of viral infection)." (PMID 40791583, 2025). "The protein IRF-3 is initially present in the cytoplasm of cells that have not been infected, but it moves to the nucleus after a viral infection occurs." (PMID 41202012, 2025). "Interestingly, it has been shown that viral infection downregulates PINK1 expression in macrophages and that PINK1 knockdown results in decreased cytokine production and attenuated IRF3 and NF-κB activation upon viral infection." (PMID 40479570, 2025). "Finally, we found that during viral infection, the overexpression of TRIM71 stabilized IRF3, and TRIM71 knockout inhibited the stabilization of IRF3." (PMID 39702801, 2025). "Interestingly, after virus infection in mice, Piezo1−/− mice presented reduced TLR9, cGAS, STING and IRF3 expression in macrophages in the BALF." (PMID 39890818, 2025). "ISG56 can be induced independently of IFN, during viral infection in cells lacking Jak1 (U4C and P2.1 cells), requiring IRF3 nuclear translocation." (PMID 39302126, 2024). "In the case of viral infection, Lgals3bp forms complex with Traf6 or Traf3, and subsequently recruits TAK1 and TBK1, which then signal the translocation of the transcription factors NF-κB, IRF3, and IRF7 from the cytoplasm to the nucleus." (PMID 38279161, 2024). "Higher levels of phosphorylated IRF3 were observed in GAPLINC knockdown cells than in control cells after IAV infection, indicating that depletion of GAPLINC enhanced the activation of IRF3 during the viral infection." (PMID 38227600, 2024). "Therefore, the ubiquitination of IRF3/7 or its upstream sensors by TRIM21, such as STING, DDX41, NMI/IFI35, and RIG-I, leads to immune suppression during virus infection." (PMID 36675197, 2023). "Mechanistically, SMYD2 inhibits IRF3 phosphorylation in macrophages in response to viral infection independent of its methyltransferase activity." (PMID 37673879, 2023). "In some virus infections, the antiviral effect is independent of IFN-I, IRF3, IRF5 or IRF7, and deficient mice survive the infection." (PMID 37737190, 2023). "After detecting viral DNA or RNA, IFI16 induces the STING-dependent signal transduction through the TBK1-mediated IRF3 axis or IKKs-mediated NF-κB axis, which results in the production of IFN-I, proinflammatory cytokines, and chemokines against viral infection." (PMID 37410794, 2023). "Furthermore, following viral infection, PRMT6 interacts with and sequesters IRF3 independently of its methyltransferase activity." (PMID 37928266, 2023). "Since IRF3 dimerization and translocation are required to activate the type I IFN pathway and the production of IFN-β during virus infection, NSP9 overexpression was performed in L929 cells and IRF3 dimerization and translocation were detected following VSV or SEV infection." (PMID 37854611, 2023).
viral infection (continued). "LXR activation has been found to blunt the TLR-dependent inflammatory response by inducing ABCA1, whereas activation of TLR3/4 during bacterial or viral infection of macrophages significantly suppressed LXR and downstream target gene expression via induction of interferon regulatory factor 3 (IRF3)." (PMID 37174692, 2023). "The importance of IRF3 and IRF7 for the survival of viral infections is controversial." (PMID 37737190, 2023). "Furthermore, we investigated IRF3-silenced cells, in which IFN production was abolished upon viral infection." (PMID 37327222, 2023). "To address whether RUNX1 could indirectly modify phosphorylation of IRF3 and STAT1 upon viral infection, we infected the cells with PR8 at an MOI of 5, collected the cells at 3, 6, and 9 h.p.i." (PMID 35248104, 2022). "Post‐translational regulations of IRF3 have profound impacts on host antiviral immunity, however, relatively little is known about the mechanism by which the biological function of IRF7 is modulated during viral infection." (PMID 35792897, 2022). "We therefore evaluated p-IRF3 levels in WT and p21-KO HEK293T cells after AH1 virus infection." (PMID 35180274, 2022). "To test whether the observed enhanced IRF3 response and IFN-stimulated gene expression increased the ability of P1 immune cells to resist viral infection, we cultured primary blasting T cells with hPIV3." (PMID 35289316, 2022). "In contrast to ruxolitinib, inhibition of LGP2 will prevent IRF3 and NF‐κB activation while minimally impacting on viral nucleic acid sensing via RIG‐I and DNA sensors, leaving patients less prone to a wide spectrum of viral infections." (PMID 35156720, 2022). "It was reported that viral infection could induce the formation of very large MAVS aggregates, which potently activate IRF3 in the cytosol; thus, we investigated whether succinate could reduce the aggregation levels of MAVS induced by VSV infection." (PMID 35309330, 2022). "Like IRF3, Interferon regulatory factor 7 (IRF7) is activated through phosphorylation and plays a pivotal role in the induction of IFN gene transcription following viral infections." (PMID 36298693, 2022). "In addition, DDOST knockdown impaired gradient viral infection (multiplicity of infection (MOI) = 1, 2, 4)-induced phosphorylation of TBK1 and IRF3." (PMID 36449507, 2022). "STING has been studied as a negative host factor for viral infections since it is a key component of the cGAS/STING/TBK1/IRF3 regulatory axis activating interferon pathway, and therefore as a target of viral immune evasion." (PMID 36455047, 2022). "In addition, IRF3 has been proven to trigger the expression of IFN and ISGs in the early stages of viral infection." (PMID 35746554, 2022). "TRIF induces IRF3, NF-κB, and MAPK kinase activation, affecting viral infections." (PMID 35563088, 2022). "IRF3 and IRF7 are the most important regulators of type I IFN against viral infection." (PMID 36330521, 2022). "The induction kinetics presented in this study suggests that CMPK2 may be induced through the LPS and Poly (I:C) mediated IRF3-type I IFN signaling pathway and is involved in the immune response against both bacterial and viral infections." (PMID 34705862, 2021). "ISG15 is one of the most highly induced ISGs in viral infections, and it has also been found to be directly induced by IRF3/IRF7, independent of IFNs (46, –, 48)." (PMID 33785572, 2021). "Moreover, virus infection-induced TNFAIP3 can block the phosphorylation and dimerization of IRF3 and inhibit the TLR3-induced activation of NF-κB and IFN-β." (PMID 34781747, 2021). "In addition to regulating apoptosis, cFLIPL has recently been shown to inhibit IRF3 and IRF7 transcriptional activation, suggesting the critical role of cFLIP in the host’s response to viral infection." (PMID 34359890, 2021). "The steady state mRNA levels of Tbk1 and Irf3 in both Mettl14+/+ and Mettl14+/− macrophages were not changed after virus infection." (PMID 34047074, 2021).
viral infection (continued). "Here we show that ARID1A is recruited by IRF3 to the promoter regions of Ifn-I, where it binds histone methyltransferase NSD2 to increase chromatin accessibility and promote IFN-I production in response to virus infection." (PMID 34315861, 2021). "After viral infection, the expression of Rubicon is increased and Rubicon suppresses interferon response by directly binding to NF-κB essential modulator (NEMO) or interferon regulatory factor 3 (IRF3)." (PMID 35083223, 2021). "Moreover, RNF5 and IRF3 showed significant translocation from the cytoplasm into the nucleus upon viral infection, which indicates that JMJD6 recruits RNF5 and IRF3 together in the nucleus upon viral infection." (PMID 33684176, 2021). "Viral infection induces the upregulation of INKIT, which is an inhibitor of NF-κB and IRF3 that restricts innate antiviral responses by depressing phosphorylation of p65 and IRF3." (PMID 33506033, 2021). "For example, the polymerase of the retrovirus HBV inhibits IRF activation, and rotavirus provides nonstructural protein 1 (NSP1) to degrade IRF3 that induces IFN response on viral infection." (PMID 32050846, 2020). "The authors suggest that this process could precisely regulate IRF3 activity and consequently the type I IFN response to viral infection." (PMID 33123162, 2020). "Exogenous rTRAIL could partially restore the expression of IRF3, IRF7, and IFN-β at early stage of viral infection (0.5–2 dpi, respectively) (compare gray column to grid column)." (PMID 32636833, 2020). "However, MAVS/IFN-β signaling by virus infection was inhibited by stress/CORT, evidenced by decreased protein level of MAVS, p-IRF3, and IFN-β, as well as declined gene level of IFN-β." (PMID 32943610, 2020). "A recent study discovered that chicken IRF7 constitutes IRF3 to mediate the relevant signaling function; thus, like in mammals, the chicken cGAS-STING-TBK1-IRF7 signaling pathway plays a critical role in circumventing virus infection." (PMID 32660114, 2020). "Transcriptomic and genomic studies have implicated alterations in key cytokines with SCZ, including increases in interferon regulatory factor 3 (IRF3), which is a major transcription factor in viral infection, and interferon gamma (IFN-γ), an important regulator of viral propagation." (PMID 33061891, 2020). "Whilst IRF-3 is constitutively expressed in all cell types, IRF-7 is constitutively expressed only in plasmacytoid dendritic cells (pDCs), while in most of the other cell types it is expressed only after viral infection." (PMID 32373120, 2020). "Viral infection promotes KAT8-mediated acetylation of IRF3 at K359, independent of the phosphorylation and dimerisation status of IRF3, and this modification interferes with binding of IRF3 to the IFNβ enhancer." (PMID 32645843, 2020). "After virus infection, CALML6 thereby impairs dimerisation and nuclear import of IRF3." (PMID 32645843, 2020). "In addition to IRF3, other IRFs have been involved in the amplification of type I IFN response following viral infection: IRF7 plays an instrumental role whereas IRF1 and IRF5, are reported to be dispensable for inducing type I IFN." (PMID 31319869, 2019). "Once STING is activated by viral infection, mitochondrial DNA or endoplasmic reticulum stress, it could recruit TANK-binding kinase 1 (TAK1) and IRF3, and then phosphorylate IRF3 by TAK1." (PMID 31121492, 2019). "Although negative regulation of IRF3 signaling is necessary to prevent persistent expression of unwanted cytokines, it may attenuate IFN response to subsequent viral infection." (PMID 31796819, 2019). "However, in contrast to constitutively expressed IRF3, the basal expression level of IRF7 is minimum but is strongly induced by type I IFN-mediated responses in an autocrine feedback loop after virus infection (discussed in detail below)." (PMID 30671058, 2018).
viral infection (continued). "Upon viral infection, SNRNP200 binds vRNA through its amino-terminal Sec 63 (Sec63-1) domain, relocates to the perinuclear region, and acts as an adaptor protein to potentiate IRF3 signaling." (PMID 29854853, 2018). "Interestingly, chickens are lacking essential components of innate immune system (e.g., RIG-I, IRF3, IRF9); they yet mount profound innate immune responses against virus infections." (PMID 30271403, 2018). "IRF3 and IRF7 are the key regulators of type I and III IFNs during viral infections." (PMID 29515574, 2018). "IRF-3 and IRF-7 could induce IFNs expression as interferon regulatory factors by nuclear-translocation upon virus infection." (PMID 30319633, 2018). "Of particular interest is DDX3X, a crucial regulator of the TBK1/IRF3 signaling leading to induction of IFN-β31,32, which may potentially modulate airway epithelial innate responses against viral infections." (PMID 29615635, 2018). "In detail, following viral infection or stimulation by specific ligands, the caspase recruitment domain (CARD) of RIG-I and MDA5 becomes accessible for NLRC5 which competes with MAVS for binding, thus leading to dampened IRF3 activation." (PMID 30344524, 2018). "Similar to the involvement of RLR-mediated type I IFN expression, IRF3 and IRF7 also contribute to the signaling pathways downstream of cytosolic DNA sensing and endosomal DNA/RNA recognition for the inductions of IFN-α and IFN-β during virus infection." (PMID 30671058, 2018). "In addition, miR-23 induced type I IFN expression through activation of IRF3/IRF7, whichmight further inhibit virus infection." (PMID 28977918, 2017). "Similar to IRF3, phosphorylation-activated IRF7 undergoes nucleus translocation and then cooperates with activated IRF3 to bind the promoter regions of IFN genes for the expression initiation following viral infection." (PMID 28286505, 2017). "IRF3 is phosphorylated and activated by active TBK-1/IKKε upon viral infection." (PMID 28589097, 2017). "Possible scenarios include that EAP30, IRF3, and CBP may assemble in different manners and possibly recruit additional factors to the promoter after virus infection." (PMID 29084253, 2017). "And the translocation of p65 and IRF3 into the nucleus was not affected either by Brd3 knockout after virus infection or LPS challenge." (PMID 28045112, 2017). "Treatment of LPS could suppress the levels by subverting the polyI:C- and viral infection-mediated TBK1, IRF3, and NF-κB response." (PMID 27826297, 2016). "Interestingly, the activation of both IRF3 and IRF7 in mammals requires virus-induced phosphorylation, coordinating the appropriate initiation of IFN responses during virus infection." (PMID 27656183, 2016). "Furthermore, because IRF-3 is degraded in A549/Npro cells, they cannot upregulate expression of IFIT1 in an IRF-3-dependent, IFN-independent manner in direct response to virus infection." (PMID 27512068, 2016). "In summary, the demonstration that phosphorylation of IRF3 contributes to inducing upregulation of SAMHD1 expression has important consequences for understanding host innate immunity and in the future management of virus infection." (PMID 27411355, 2016). "In response to viral infection, accumulated and aggregated mitochondrial antiviral-signaling proteins (MAVS) on the mitochondrial outer membrane (OMM) activate interferon regulatory factor 3 (IRF3) and NF-κB." (PMID 28074080, 2016). "Considering that interferon expression is mainly IRF3/IRF7-mediated while expression of TNFα and CXCL8 is mainly NFκB-mediated, it appears that azithromycin predominantly affects IRF signalling pathways after viral infection." (PMID 27350308, 2016). "Viral infection results in the activation of IRF-3 and the low-level secretion of IFN-α on non-plasmacytoid DCs." (PMID 27285980, 2016).